UBE2Z (ubiquitin conjugating enzyme E2 Z)
Description:
Catalyzes the covalent attachment of ubiquitin to other proteins (By similarity). Specific substrate for UBA6, not charged with ubiquitin by UBE1. May be involved in apoptosis regulation.
Synonyms: Use1; HOYS7; FLJ13855
Tractability: PROTAC: ubiquitination databases record sites on it; its protein half-life has been measured.
Gene: Protein-coding gene on chromosome 17 (48,908,398 to 48,929,056, forward strand). Ensembl gene ENSG00000159202.
Subcellular location: Cytoplasm; Nucleus
Subcellular location (Human Protein Atlas): Cytosol; Nucleoplasm
Pathways (Reactome):
Immune System: Antigen processing: Ubiquitination & Proteasome degradation
Metabolism of proteins: Synthesis of active ubiquitin: roles of E1 and E2 enzymes
Gene Ontology:
Molecular function: molecular adaptor activity; protein binding; ubiquitin conjugating enzyme activity
Biological process: positive regulation of apoptotic process; negative regulation of apoptotic process; protein ubiquitination
Cellular component: cytosol; nucleoplasm; nucleus; cytoplasm
Genetic constraint (gnomAD): Loss-of-function variants: 7 observed, 23.54 expected, observed/expected ratio (o/e) 0.3, 90% interval 0.17 to 0.56. The upper end of that interval is the gene's LOEUF score, 0.56, which puts it in group 2 of 6, group 1 being the genes least tolerant of losing a copy. Missense variants: 330 observed, 403.47 expected, observed/expected ratio (o/e) 0.82, 90% interval 0.75 to 0.9. Synonymous variants: 176 observed, 157.26 expected, observed/expected ratio (o/e) 1.12, 90% interval 0.99 to 1.27.
Homologues: Orthologues: chimpanzee UBE2Z (100% identical), pig UBE2Z (99% identical), rat Ube2z (99% identical), mouse Ube2z (99% identical), dog UBE2Z (99% identical), macaque UBE2Z (96% identical), guinea pig UBE2Z (76% identical), zebrafish ube2z (69% identical), tropical clawed frog ube2z (69% identical), rabbit UBE2Z (67% identical). Paralogues in human: UBE2O (31% identical), UBE2T (15% identical), CDC34 (15% identical), UBE2N (15% identical), UBE2R2 (14% identical), UBE2S (14% identical), UBE2B (14% identical), UBE2A (14% identical), UBE2NL (13% identical), UBE2W (13% identical), UBE2I (13% identical), UBE2G1 (13% identical), and 12 more.
Diseases named in the same sentence as UBE2Z in open-access papers:
UBE2Z is named in the same sentence as 19 diseases in open-access papers, as found by Europe PMC text mining. Sharing a sentence is not in itself a finding about the gene and the disease. The quoted sentences say what the papers report.
coronary artery disease (4 papers, 2017 to 2023). "Although this gene has not been previously been studied for its role in beta cells, UBE2Z was also reported to be associated with coronary artery disease in different populations." (PMID 30956117, 2019). "As a coronary artery disease-related variant, rs46522 at the UBE2Z locus yielded significant association with type 2 diabetes in a genome-wide association study." (PMID 28840129, 2017). "Furthermore, variants of the ubiquitin-conjugating enzyme E2Z gene (UBE2Z) are significantly associated with hypertriglyceridemia as well as being a possible risk factor for coronary artery disease." (PMID 36769149, 2023). "Partial QTLs or SNPs have been associated with coronary artery disease (SNF8 and UBE2Z)." (PMID 35052342, 2021).
hepatocellular carcinoma (4 papers, 2021 to 2025). A malignant tumor that arises from hepatocytes. "In hepatocellular carcinoma, UBE2Z is overexpressed in tumor tissues and is significantly associated with TNM stage and histological grade." (PMID 35127943, 2022). "Ubiquitin Conjugating Enzyme E2 Z (UBE2Z) is involved in the degradation of defective proteins and has been shown to be highly expressed in hepatocellular carcinoma compared to healthy controls and results in poor prognosis." (PMID 35711821, 2022).
breast carcinoma (2 papers, 2021 to 2025). "In the analysis of the correlation between overall survival and significant DEG expression (CLDN7, MLLT10, RBM33, SH3RF1, SSBP4, and UBE2Z) in breast cancer, we found a shorter survival time based on GSE5881 and GSE42568 (P< 0.05)." (PMID 34151730, 2021). "Significantly overexpressed genes (CLDN7, MLLT10, RBM33, SH3RF1, SSBP4, and UBE2Z) were correlated with shorter survival, whereas underexpressed genes (BMPER, FGF7, MSRB3, and TNRC6B) were correlated with longer survival in breast cancer." (PMID 34151730, 2021). "UBE2Z is a ubiquitin-conjugating enzyme with potential involvement in the regulation of apoptosis, among other critical cellular processes, but it has no known role in breast cancer." (PMID 41516236, 2025). "Interestingly, other DEGs in breast cancer identified in this study, including MLLT10, RBM33, SH3RF1, UBE2Z, and TNRC6B, have not been proven in previous studies." (PMID 34151730, 2021).
frontotemporal dementia (2 papers, 2024 to 2025). Frontotemporal dementia (FTD) comprises a group of neurodegenerative disorders, characterized by progressive changes in behavior, executive dysfunction and language impairment, as a result of degeneration of the medial prefrontal and frontoinsular cortices. "Other UBE2 enzymes, such as UBE2I, UBE2Q1, UBE2E1, and UBE2Z, display varied regulatory patterns in neurodegenerative diseases like frontotemporal dementia, suggesting the Ube2 family’s extensive influence on neurodegeneration, inflammation, and cellular stress responses." (PMID 39108475, 2024).
insomnia (2 papers, 2023 to 2025). A sleep disorder characterized by difficulty in falling asleep and/or remaining asleep. "Genome-wide association studies identified a genetic locus (near ATP5G1, UBE2Z, SNF8, IGF2BP1 and GIP) linked to insomnia and CVD." (PMID 40176577, 2025). "Similarly, UBE2Z, GIP and IGF2BP1 have been linked to CAD, T2D, and depression-related traits such as insomnia, BMI, educational attainment, CRP levels, platelet count and smoking." (PMID 37390107, 2023). "This study is the first to identify four genes at a single locus that link CVD and insomnia: ATPsynC, Bruce, lsn and Imp (ATP5G1, UBE2Z, SNF8 and IGF2BP1 in humans)." (PMID 40176577, 2025).
lung carcinoma (2 papers, 2017 to 2021). "The overexpression of UBE2Z significantly increases cell proliferation, migration, and invasion of lung cancer cells in vitro, while its knockdown suppressed these phenomena." (PMID 34199813, 2021). "A recent report showed that UBE2Z is frequently overexpressed in lung cancer, proposing a cell cycle promoting ability of the E2 enzyme." (PMID 29152096, 2017). "Taken together, these reports denoted that targeting UBE2Z could be a novel strategy for lung cancer therapies." (PMID 34199813, 2021).
esophageal cancer (1 paper, 2023). A primary or metastatic malignant neoplasm involving the esophagus. "constructed a prognostic map for esophageal cancer, utilizing eight genes, including CDCA4, UBE2Z, AMTN, AK1, TLE1, FXN, ZBTB6, and APLN." (PMID 38098487, 2023).
Type 2 Diabetes (1 paper, 2017). "In conclusion, the study showed that rs46522 in UBE2Z gene contributed to the development of CAD in individuals of Chinese Han descent with type 2 diabetes and had an interactive effect with BMI on CAD risk." (PMID 28840129, 2017). "The SNP rs46522 in UBE2Z gene is associated with the risk of CAD in the individuals of Chinese Han descent with type 2 diabetes and is of synergistic effect with BMI." (PMID 28840129, 2017). "We investigated the association between ubiquitin-conjugating enzyme E2Z (UBE2Z) gene SNP rs46522 and the risk of CAD in a Chinese Han population with type 2 diabetes and explored a possible interactive effect with environmental risk factors of CAD." (PMID 28840129, 2017). "In the study, SNP rs46522 in UBE2Z was found contributing to the development of CAD in Chinese Han population with type 2 diabetes." (PMID 28840129, 2017). "Exploration could be made to discover the mechanism of UBE2Z locus affecting both CAD and type 2 diabetes in a molecular level." (PMID 28840129, 2017).
tumor (5 papers, 2021 to 2025). "The levels of HLA-E and UBE2Z were higher in lymphocytes, and their expression levels were correlated with the infiltration levels of B cell and T cell in tumor tissue." (PMID 35127943, 2022). "Gene knockout analysis of UBE2Z using siRNA has been found to drastically reduce tumor cell proliferation, migration and invasion." (PMID 35711821, 2022). "Conversely, an 87% reduction of tumor growth was observed in mice injected with UBE2Z-depleted cells." (PMID 34199813, 2021). "Furthermore, we evaluated the correlations between UBE2Z expression and pathologic parameters (histologic grade, tumor size, and nodal metastasis)." (PMID 41516236, 2025). "In addition, xenograft models showed that mice bearing UBE2Z-overexpressing cells showed approximately three-fold higher tumor formation than mice bearing control cells." (PMID 34199813, 2021). "These intrinsic events within tumor cells enhance ER stress‐associated ubiquitylation and degradation by triggering ubiquitin via the E1 activase UBA6, facilitating ubiquitin transferring to E2 conjugate UBE2Z and increasing the activities of E3 ligase FBXW7 to degrade both EZH2 and MYC." (PMID 39823459, 2025). "CAPZA1, HLA-E, IMPA2, NFE2L3, PLEKHO1, SIGLEC1, and UBE2Z were expressed at higher levels in tumor tissues, whereas EMX2, FGL2, FUCA1, and GRB2 were expressed at lower levels in tumor tissues." (PMID 35127943, 2022). "During tumor progression, CAPZA1, GRB2, NF2EL3, PLEKHO1, SIGLEC1, and UBE2Z were expressed at higher levels in late-stage KIRC, whereas EMX2, FUCA1, IMPA2, and RORC were expressed at higher levels in early-stage KIRC." (PMID 35127943, 2022). "However, the level of UBE2Z did not correlate with either the histologic grade or the tumor size." (PMID 41516236, 2025).
cancer (3 papers, 2021 to 2025). A tumor composed of atypical neoplastic, often pleomorphic cells that invade other tissues. "However, at present, research on the role of UBE2Z in cancer development and progression is very limited." (PMID 41516236, 2025). "Future research analyzing the role of UBE2Z in various types of cancer is warranted." (PMID 41516236, 2025). "Notably, we found SRSF1, HECW2, SRSF6, UBE2Z and PCF11, to be linked to carcinogenesis and cancer management 51-62 and are associated with poor prognosis in HMs." (PMID 35711821, 2022). "SNF8, UBE2Z, CALCOCO2, and ATP5MC1 have been shown a core function in metabolic disease and cancer." (PMID 35052342, 2021).
gastrointestinal tumors (1 paper, 2025). "Importantly, our observations uncover a novel ubiquitination cascade composed of UBA6, UBE2Z, and FBXW7 that may regulate the degradation of the squamocin‐induced EZH2/MYC axis in pan‐gastrointestinal tumors." (PMID 39823459, 2025).
UBE2Z also shares sentences with these, for which no sentence is quoted: neurodegenerative disease (2 papers); coronary stenosis (1); depression (1); glioma (1); hematological malignancies (1); hypertriglyceridemia (1); metabolic disease (1); migraine (1).